CDH1 (cadherin 1)
Diseases named in the same sentence as CDH1 in open-access papers (continued):
Sharing a sentence is not in itself a finding about the gene and the disease.
tumor (continued). "In addition, we uncovered an inverse correlation between miR-25 and CDH1 in NSCLC tumor tissues and cell lines." (PMID 31208279, 2019). "Alternatively, cisplatin may elicit a change in expression in the CDH1-negative tumor cells (i.e., a reduction in replication rate that contributes to cisplatin resistance and may lead to concomitant re-expression of CDH1)." (PMID 31189116, 2019). "On the contrary, under combined stimuli, H19 level is transcriptionally reduced, and CDH1 and β integrin expression released, switching tumor dissemination toward an alternative mechanism, the cohesive phenotype, suggesting a tumor suppressor role for H19 in this condition." (PMID 31426484, 2019). "Possibly, in vitro propagated cells or PDX lines still do not reflect the primary tumor, or the association of CDH1 expression with chemotherapy exposure is accidental." (PMID 31189116, 2019). "We studied a retrospective cohort of 160 consecutive surgically treated NSCLC patients with available frozen tumor samples for expression of EMT markers (CDH1, CTNNB1, CDH2, and VIMENTIN), inducers (TGFB1, c‐MET, and CAIX), and transcription factors (EMT‐TF:SNAI1, SNAI2, ZEB1, TWIST1, and TWIST2)." (PMID 29845746, 2018). "A loss of epithelial(E)-cadherin (CDH1) expression or function diminishes the strength of cellular adhesion within a tissue and results in an increase in cellular motility that correlates with tumor progression and metastasis." (PMID 29783778, 2018). "The recent studies have shown that CDH1 is functioning as a tumor suppressor whereas CDC20 may function as an oncogene to promote the development and progression of human cancers." (PMID 30563222, 2018). "Like BRCA2- and CHEK2-associated tumours, ATM-associated tumours are mostly luminal tumours but they do not show a particular histological subtype as observed in BRCA1- (medullary), BRCA2- (lobular), CDH1- (lobular), and PTEN-associated tumours (apocrine)." (PMID 29665859, 2018). "Different from other tumor repressors, complete loss of CDH1 expression is not sufficient for the development of invasive carcinoma, as has been demonstrated in transgenic animal models." (PMID 30568591, 2018). "Tumor cells in classic ILC are small and round and invade the stroma in a discohesive single-file pattern, which can be attributed largely to the loss of E-cadherin (CDH1)." (PMID 30180878, 2018). "While CDC20 has been linked to cancer progression, the second APC co-activator, CDH1, has been linked to tumor suppression, with earlier work demonstrating that cells lacking CDH1 have a shortened G1 phase, accumulate DNA damage, and undergo apoptosis." (PMID 29954095, 2018). "Furthermore, Cdh1 protein, whose loss is a key contributor to EMT, tumor malignancy, and progression, was also substantially downregulated in islets and tumors." (PMID 30405106, 2018). "For example, the correlation of CDH1 mutations to the activation of WNT, EGFR, and AKT pathways as well as the inactivation of tumor suppressors, such as EPHB3 and IGSF8, provides several hypotheses to test." (PMID 29520031, 2018). "Univariate analyses showed that lack of expression of CDH1, tumor size and nodal status were significantly associated with worse RFS and OS (p< 0.05)." (PMID 29100362, 2017). "In contrast, our analysis included only primary tumor specimens, and the restriction to carcinomas provided the most plausible scenario in which detachment would involve low cancer cell expression of CDH1, given that CDH1 is a critical epithelial cell-cell adhesion molecule." (PMID 29156750, 2017). "CDH1 is epigenetically silenced in many epithelial cancers and this event is associated with the epithelial-to-mesenchymal transition (EMT) and the acquisition of cancer stem-like cell (CSC) properties, key features in tumour progression." (PMID 28555645, 2017). "Down-regulation of CDH1 promotes malignant transformation, tumor invasion and metastasis." (PMID 29285016, 2017).
tumor (continued). "Furthermore, CDH4 suppression resulted in down-regulation of E-cadherin (E-cad), which is encoded by CDH1 gene and is a well-known tumor suppressor gene by inhibition of cell proliferation and migration." (PMID 27783992, 2016). "Whether the tumor-suppressive function of Cdh1 also involves its role in controlling cell fate after DNA damage is unclear." (PMID 26650195, 2016). "Interestingly, higher cytoplasmic CDH1 expression was observed in PC samples; 33.3% of tumor samples (28/84) but only 11.9% (10/84) of adjacent tissue samples displayed high cytoplasmic CDH1." (PMID 26918727, 2016). "Similarly, the decrease in MMP2/9 mRNA levels and the increase in CDH1 mRNA level were observed in tumor tissue using Real-time PCR analysis (the lowest panel, *P < 0.05, **P < 0.01, ***P < 0.001, vs control)." (PMID 26811493, 2016). "Neither cytoplasmic nor membrane CDH1 were associated with patients’ gender, age, tumor location, tumor size, tumor differentiation, invasion depth, distant metastasis, abdominal pain, jaundice or nervous invasion (P > 0.05)." (PMID 26918727, 2016). "Using the Cancer Genome Atlas UBC tumor collection, we evaluated whether PTEN loss of function was linked to E-cad (CDH1) downregulation or N-cad (CDH2) expression." (PMID 27863432, 2016). "Furthermore, gene expression of CDH-1 was analyzed as a marker for tumor invasiveness in mammary tissues showing different degrees of malignancy." (PMID 26370564, 2015). "Our data revealed that the outcome of MSC–tumor interaction is dependent on the nature rather than the type of tumor cells and that epithelial cadherin type 1 (CDH1) and IL-1β expression by tumor cells are key factors in determining the outcome of hMSC–tumor cross-talk." (PMID 26204886, 2015). "During tumour development and in particular during metastasis, the inactivation of CDH1 or alternatively the activation of PTK2 could be two disjoint paths to achieve cell migration to distant sites." (PMID 26427375, 2015). "We then asked whether this nuclear staining could be a specific property of the strongly proliferating tumor cells and specific for CDH1." (PMID 26029826, 2015). "CDH1 levels decreased while CDH2 levels increased in siIGFBP2/CDDP-treated Flo-1 cells as compared to mock-treated or siNon-targeting controls, indicating an “E-cadherin to N-cadherin switch” that has been previously shown to contribute to tumor cell motility and invasion." (PMID 26317790, 2015). "Furthermore, miR-25 was found to promote ESCC cell migration and invasion by suppressing the expression of E-cadherin (CDH1), a very important tumour metastasis suppressor." (PMID 24651474, 2014). "Since CDH1 is a regulator of the epithelial-to-mesenchymal transition, this result is potentially relevant to understanding the activity of ROS in silencing tumor suppressor genes, and in subsequent tumor progression and metastasis." (PMID 25120642, 2014). "CDH1 protein detection was performed only for patient AM05, a carrier of the germline mutation 185 G > T and member of family A. This patient died before the start of the study, and a genetic analysis was performed on a paraffin-embedded tumor tissue." (PMID 25180051, 2014). "However, only calcitriol increased expression of the pro-differentiation marker, cadherin 1 (p = 0.0086), and reduced tumor proliferation (p = 0.0467)." (PMID 24586868, 2014). "The tumor suppressor role of CDH1 in NB metastasis may explain the manner in which the upregulation of miR-23a promotes NB cell migration and invasion and contribute to the transformation of primary to metastatic NB." (PMID 24520301, 2014). "Accumulating previous evidence has suggested that genetic or epigenetic alterations in CDH1 or alterations in their protein expression, often result in tissue disorder, cellular dedifferentiation, increased invasiveness of tumor cells and ultimately metastasis." (PMID 24520301, 2014).
tumor (continued). "Interestingly, the partners of ANAPC2, CDC20 and CDH1, were also upregulated in this tumor, and APC/C has a recently-documented important role in cancer, and can be inhibited with a small molecule (Tosyl-L-Arginine Methyl Ester)." (PMID 25155515, 2014). "CDH1 transcriptional repressors, such as SNAI1 (SNAIL), SNAI2 (SLUG), ZEB1, ZEB2 (SIP1), E12/E47, and TWIST have traditionally been implicated in promoting EMT in various systems of embryonic development and tumor progression." (PMID 24968068, 2014). "A reduction in CDH1 increases cell mobility and promotes tumor cell invasion." (PMID 23437057, 2013). "Using ILBC cell lines, primary tumors and pre-invasive lesions as a model, the present work aimed to determine whether reciprocal upregulation of BCL2 is an important determinant of tumor development driven by inactivation of CDH1/E-cadherin." (PMID 24023670, 2013). "Notably, LEF1 was identified as a regulator of FN1 and CDH1 expression in tumor-derived cells and was proposed to act in both, a CTNNB1-dependent as well as -independent manner." (PMID 23677615, 2013). "Of interest, this mutation was already detected in a healthy 41-year-old Japanese subject, with no clinically detectable tumor at the time of the enrolment, and described as a rare variant able to decrease the transcriptional activity of CDH1." (PMID 24204729, 2013). "The detection of CDH1 methylation in PPW could be very applicable guidance for the diagnosis of tumor invasion and metastasis, also for prediction of progression and prognosis in GC." (PMID 22514028, 2012). "Corresponding results were, for CDH1 (1 tumor with mean >10% and 1 additional tumor with max at 17%), for RASSF2 (1 tumor + 24 tumors up to 15%), for DCR2 (5 tumors + 3 tumors up to 39%), for RASSF1A (23 tumors + 1 up to 31%), and for CASP8 A1 (21 tumors + 2 tumors up to 21%)." (PMID 22984959, 2012). "Indeed, it has been found that a number of APC/C substrates are frequently overexpressed in malignant tumors and, given its role in preventing genomic instability, Cdh1 has been proposed as a tumour suppressor." (PMID 21886810, 2011). "Recently, it has been postulated that Twist, another promoter repressor of CDH1 (E-cadherin gene), may be involved in tumor progression by silencing E-cadherin expression and EMT induction." (PMID 20809941, 2010). "In 4T1 tumor cells, CDH1 was highly expressed compared to 168FARN or 4T07 cells." (PMID 20700505, 2010). "Given the universal expression of E-cadherin in epithelial tissues, this exploratory study may also provide a basis to investigate the role of the CDH1 163+37235G>A SNP in the incidence and progression of tumours other than DGC." (PMID 18482459, 2008). "After analyzing the methylation levels of the genes that were differentially methylated among the four tumor subtypes, empirical cutoff values were established to maximize the discriminative power of each gene (2.0 for CDH1, 80.0 for PTGS2, and 230.0 for RASSF1A)." (PMID 17645803, 2007). "Compelling experimental evidence indicates that the CDH1 gene is a tumor suppressor." (PMID 16512896, 2006). "In our study, DUSP5 exhibited intermediate expression relative to JUNB and CDH1, and its expression was lower in cells cultured in the 3LBNC scaffold compared to conventional plate culture, further supporting the scaffold’s ability to replicate features of the in vivo tumor microenvironment." (PMID 40558895, 2025). "Based on these transcriptomic results, suppression of CCN2, FGFR2, and SELE may inhibit tumor proliferation, metastasis, or angiogenesis, while upregulation of CDH1 and CXCL10 could enhance cellular adhesion and antitumor immune responses, offering promising avenues for therapeutic intervention." (PMID 40724877, 2025).
tumor (continued). "E-cadherin (E-cad) is a member of Ca2+-dependent membrane glycoprotein, encoded by CDH1 gene which is crucial for preserving epithelial cell-cell junctions and cell polarity, and suppresses tumor growth, metastasis and invasion in numerous cancers comprising GC." (PMID 38870263, 2024). "Tumor mutational burden (TMB) was not significantly different between the CDH1-altered and -unaltered groups (p = 0.05); 84.1% of the CDH1-altered group had a low TMB and 15.9% had a high TMB, whereas 88.3% of the CDH1-unaltered group had a low TMB and 11.7% had a high TMB." (PMID 39201647, 2024). "As shown in circos diagram of MF, HSP90AA1 and CDH1 (E-Cadherin) were highly enriched in the cytoskeleton, suggesting that HSP90AA1 may profoundly change the characteristics of tumor cells through the cytoskeleton, thus causing the epithelial tumor cells may EMT." (PMID 37547757, 2023). "Additionally, some DGC patients tested negative for CDH1/CTNNA1 gene but had pathogenic variants in related tumor susceptibility genes, such as BRCA2, ATM, SDHB, PRSS1, MSR1, STK11, and PALB2." (PMID 37393258, 2023). "Thus, while larger imaging studies of CDH1-associated ILC may elucidate important diagnostic and potential phenotypic tumor characteristics, biopsy with histopathologic analysis will likely remain the diagnostic gold standard for these lesions." (PMID 37758801, 2023). "With an inherited germline CDH1 mutation coupled with inactivation of the wild-type allele, HDGC is likely a multi-stage process with initial loss of E-cadherin and disruption of apical-basal cell polarity which enables tumour cells to detach from the basement membrane." (PMID 36869400, 2023). "Thereby, it was suggested that EGCG may serve as a potential epigenetic modifier by altering the methylation status of genes encoding retinoic acid receptor beta (RARβ), cadherin 1 (CDH1), and death-associated protein kinase 1 (DAPK1) tumor suppressors to reactivate their expression." (PMID 37446908, 2023). "However, the effect of haploid gain and loss was not confined to CDH1 but also seen in other known or putative oncogenes and tumour suppressor genes, although the effect was highly variable across genes." (PMID 37495687, 2023). "Studies have shown that FOXA2 could function as a tumor suppressor by selectively binding to the promoter of several genes related to epithelial–mesenchymal transition (EMT), such as Slug, CDH1 or Zeb2, to suppress tumor migration and progression in lung cancer, breast cancer or liver cancer." (PMID 38072043, 2023). "Based on the CCLE database, CDH1 was also significantly overexpressed in several different cancer cells, derived from the urinary tract, breast, lung, cholangio, prostate, esophagus, colorectal, and endometrium, which generally conformed to that in tumor tissues." (PMID 36131343, 2022). "Amongst the tumour where we analysed DCIS with strong E-cadherin protein expression, no CDH1 mutations or promoter methylation were observed, suggesting that divergence from ductal morphology in the in-situ disease to a lobular morphology is due to additional mechanisms." (PMID 35053458, 2022). "Notably, enforced stratifin (14‐3‐3σ; SFN) overexpression could increase pT606‐Kaiso accumulation in the cytoplasm and de‐repress the transcription of Kaiso target gene cadherin 1 (CDH1), which is a tumour suppressor." (PMID 35851744, 2022). "We next sought to assess if somatic mutations in the promoter regions of CDH1, and α-, β- and γ-catenin could explain the heterogeneity of E-cadherin in these tumours lacking CDH1 mutations." (PMID 35053458, 2022). "Taken together, these results suggest that genomic alterations of CDH1 may explain the differential pattern of E-cadherin protein expression of a subset of EcadhetILC tumours; however, in the majority of cases, the differences in E-cadherin expression could be due to additional mechanisms." (PMID 35053458, 2022).
tumor (continued). "Previous studies demonstrated that the mechanisms of immune resistance to ICIs might involve mutations in the Wnt/β-catenin pathway, PI3K-AKT-mTOR pathway, CDH1 gene, elevated expression of Dickkopf 1 (DKK1), and heterogeneity in tumor mutation burden and tumor microenvironment." (PMID 36291942, 2022). "Thus, we hypothesize that Cdh1 deletion can greatly improve the sensitivity of tumor cells to PARP inhibitors." (PMID 35627188, 2022). "Therefore, increased CDH1 expression appears to improve tumor immunity by inhibiting pDCs and macrophage and neutrophil accumulation and by reducing Treg generation via the suppression of pDCs to restrict the escape of cancer cells from annihilation and, ultimately, relieve tumorigenesis." (PMID 36131343, 2022). "In order to analyze whether this alteration affected the translational level, we explored these two promising candidates (CD44 and CDH1) and their potential clinical impact by evaluating a cohort of 100 patients with unique tumor location at the tongue followed-up by 10 years." (PMID 33976322, 2021). "Lack of a detectable CDH1 mutation may also be related to insufficient sequencing depth or low tumor cellularity." (PMID 34359596, 2021). "These patterns are intimately linked to E-cadherin: ILCs do not express CDH1 due to the presence of inactivating mutations or silencing via methylation, or copy loss, and hence grow as individual and linear arrays of tumour cells." (PMID 33276802, 2020). "Fusobacterium sequences were enriched in carcinomas, which could bind to host epithelial Cadherin 1 through the adhesion of FadA and invade epithelial cells from through the E-cadherin/β-catenin signaling to induce inflammation and tumor cell growth in transformed cells." (PMID 33330121, 2020). "For example, the CDH1 gene, thought to be related to nsCL/P and cancer subtypes, has been shown to be related to both axonal growth and patterning in the developing murine brain (Konishi, Stegmüller, Matsuda, Bonni, & Bonni, 2004), and tumour suppression (Berx, Becker, Höfler, & Van Roy, 1998)." (PMID 32710482, 2020). "We analyzed the mRNA level of tumor-associated genes such as Cadherin-1, Ki-67, PCNA, β-catenin, STAT3, and COX2, as well as the protein levels of tumor marker VEGF, its downstream transcription activator STAT3 and p-STAT3, and the tumor proliferation marker PCNA." (PMID 32582527, 2020). "Similarly, the change in expression of E-cadherin to N-cadherin or the up-regulation of cadherin-11 and P-cadherin also favor tumor progression and are an indicator of more migratory and more invasive tumor types." (PMID 33076339, 2020). "In this approach, we hypothesised that if a genuine SL interaction exists between E-cadherin and any given pathway or protein, there would be fewer tumours than expected by chance with low expression (relative to all tumours) of both CDH1 and the pathway or protein." (PMID 30066183, 2019). "It was hypothesized that overexpression of CDH1 might have an impact on oncogenesis since previous research has indicated the intercellular adhesion between cancer and normal cells were enhanced in the late stage of tumor formation." (PMID 31598425, 2019). "For example, mutated CDH1 was associated with differential TAC mRNA abundance for genes involved in immune activation and proliferation suggesting non-silent CDH1 mutations may dysregulate immune cells in the tumour microenvironment." (PMID 31308365, 2019). "Tumor cells undergoing transient hypermethylation leading to silencing of CDH1 transcription are more aggressive, but eventually E-cadherin is re-expressed in metastases due to the demethylation of the CDH1 gene promoter, highlighting a high degree of epigenetic plasticity in tumor cells." (PMID 31557902, 2019). "However, it remains poorly characterized for the population of APC-free Cdh1 in tumor cells." (PMID 31420536, 2019).